PCYT2 (phosphate cytidylyltransferase 2, ethanolamine)
Description:
Ethanolamine-phosphate cytidylyltransferase that catalyzes the second step in the synthesis of phosphatidylethanolamine (PE) from ethanolamine via the CDP-ethanolamine pathway. Phosphatidylethanolamine is a dominant inner-leaflet phospholipid in cell membranes, where it plays a role in membrane function by structurally stabilizing membrane-anchored proteins, and participates in important cellular processes such as cell division, cell fusion, blood coagulation, and apoptosis.
Synonyms: ET; SPG82
Tractability: Small molecule: a structure with a bound ligand is known; it has a high-quality binding pocket. PROTAC: ubiquitination databases record sites on it; its protein half-life has been measured.
Gene: Protein-coding gene on chromosome 17 (81,900,958 to 81,911,461, reverse strand). Ensembl gene ENSG00000185813.
Subcellular location (Human Protein Atlas): Cytosol; Nucleoplasm
Pathways (Reactome):
Metabolism: Synthesis of PE
Gene Ontology:
Molecular function: ethanolamine-phosphate cytidylyltransferase activity; protein binding; catalytic activity
Biological process: phosphatidylethanolamine biosynthetic process; phospholipid biosynthetic process
Cellular component: endoplasmic reticulum membrane
Genetic constraint (gnomAD): Loss-of-function variants: 34 observed, 50.11 expected, observed/expected ratio (o/e) 0.68, 90% interval 0.51 to 0.9. The upper end of that interval is the gene's LOEUF score, 0.9, which puts it in group 3 of 6, group 1 being the genes least tolerant of losing a copy. Missense variants: 425 observed, 513.62 expected, observed/expected ratio (o/e) 0.83, 90% interval 0.76 to 0.9. Synonymous variants: 239 observed, 200.42 expected, observed/expected ratio (o/e) 1.19, 90% interval 1.07 to 1.33.
Homologues: Orthologues: chimpanzee PCYT2 (100% identical), guinea pig PCYT2 (92% identical), rat Pcyt2 (92% identical), pig PCYT2 (92% identical), mouse Pcyt2 (92% identical), dog PCYT2 (88% identical), macaque PCYT2 (87% identical), zebrafish pcyt2 (77% identical), tropical clawed frog pcyt2 (76% identical), Drosophila melanogaster Pect (59% identical), Caenorhabditis elegans pcyt-2.1 (55% identical), Caenorhabditis elegans pcyt-2.2 (31% identical). Paralogues in human: PCYT1A (22% identical), PCYT1B (21% identical).
Diseases named in the same sentence as PCYT2 in open-access papers:
PCYT2 is named in the same sentence as 46 diseases in open-access papers, as found by Europe PMC text mining. Sharing a sentence is not in itself a finding about the gene and the disease. The quoted sentences say what the papers report.
Obesity (9 papers, 2013 to 2025). Accumulation of substantial excess body fat. "Together the inherent transcriptional and metabolic adaptations to reduced Pcyt2 expression and activity cause a progressive metabolic dysfunction, culminating in obesity, insulin resistance, and hypertriglyceridemia." (PMID 35058529, 2022). "Even the disruption of one allele of Pcyt2 in the Pcyt2+/−mouse has major physiological effects as these animals develop insulin resistance, obesity, dyslipidaemia and liver steatosis, the hallmarks of metabolic syndrome." (PMID 31637422, 2019). "Taken together, the biochemical, and expression analysis established that supplementation of Bet had a significant lipid-lowering effect on Pcyt2 deficient obesity model." (PMID 30042948, 2018). "In our previous study, we showed that Pcyt2 deficiency induces NASH characterized by hyperglycemia, increased glycogen and TAG accumulation, inflammation, fibrosis, and obesity." (PMID 40153413, 2025). "PCYT2 is instrumental in the deregulation of these processes leading to the development of obesity, insulin resistance, liver steatosis and dyslipidemia." (PMID 40434993, 2025). "In animal studies, genetic defects in CTP:phosphoethanolamine cytidylyltransferase (Pcyt2), a key enzyme of hepatic PC synthesis, led to obesity and obesity-related HS development." (PMID 35057441, 2022). "Here, we show that Pcyt2+/− mice are an ideal translation model for the human disease because they develop NASH over time and within the context of key risk factors for the human condition (obesity and metabolic syndrome)." (PMID 35058529, 2022). "The liver-specific Pcyt2−/− knockout develops steatosis but neither obesity nor insulin resistance, showing that multiple-organ Pcyt2 deficiency was a critical factor for development of the metabolic disease phenotype." (PMID 23354482, 2013). "Therefore, an obesity-induced decrease in PCYT2 expression and an increase in PEMT expression may result in decreased PE synthesis, and increased transformation may be the cause of this decreased expression." (PMID 38640132, 2024). "On the other hand, although the phenotype of Pcyt2+/− mice is identical with the littermate controls during the first 2 months of age, Pcyt2 +/− mice progressively gaine weight which at 24–28 weeks of age leads to the development of adult-onset hypertrigyceridemia, liver steatosis and obesity." (PMID 23354482, 2013). "As demonstrated via several lines of evidence obtained from cell culture and animal models, Pcyt2 plays a pivotal role in the execution of the processes deregulation of which could lead to the development of obesity, insulin resistance, liver steatosis and dyslipidemia." (PMID 23354482, 2013). "For example, Aida deficiency causes severe obesity, hypertriglyceridemia and increased intestinal lipid absorption in mice; thus, the failure of PEA to reverse the aberrant methylation and expression of Aida may impede the full resolution of the Pcyt2 + /- phenotype." (PMID 40153413, 2025). "Pcyt2 heterozygous mice (HET) progressively gain weight and develop hypertriglyceridemia, liver steatosis, and obesity." (PMID 30042948, 2018). "Younger Pcyt2+/− mice experience elevated expression of SREBP1 and lipogenesis; however, they develop fatty liver, obesity, and insulin resistance at later stages." (PMID 23354482, 2013).
Insulin resistance (8 papers, 2013 to 2025). Increased resistance towards insulin, that is, diminished effectiveness of insulin in reducing blood glucose levels. "Similarly, insulin-resistant mice deficient in CTP:phosphoethanolamine cytidylyltransferase deficient (Pcyt2) had increased protein synthesis and turnover within skeletal muscle with choline supplementation." (PMID 36689425, 2023). "Additionally, Drosophila with Pect deficiency (the analog of PCYT2), develop insulin resistance and have a disrupted hunger response." (PMID 36687696, 2022). "Adult (6-8-mo) Pcyt2 + /- mice exhibit insulin resistance and develop NASH that is characterized by increased glucose production, accumulation of TAG and glycogen, and increased inflammation." (PMID 40153413, 2025). "Although the role of Pcyt2 in the development of insulin resistance in muscle is evident, elucidation of molecular mechanisms behind it require further studies that should take into account the numerous factors involved in multiple levels of regulation." (PMID 23354482, 2013). "We have previously shown that Pcyt2 + /- insulin resistance and NASH develop at 6-8-mo." (PMID 40153413, 2025). "Our subsequent studies established that the Pcyt2+/– mouse is a model for non-alcoholic steatohepatitis (NASH) and insulin resistance, and that supplementation with phosphoethanolamine helps to reverse NASH symptoms." (PMID 36687696, 2022).
breast carcinoma (6 papers, 2008 to 2025). "The changes observed in alternative splicing of PCYT2 in breast cancer cells highlight the importance of PCYT2 regulation." (PMID 35563655, 2022). "One of these genes was the PCYT2 gene, highlighting the importance of PCYT2 in relation to breast cancer." (PMID 35563655, 2022). "The data shows that the splicing of the PCYT2 gene is altered in cancer cells, as evidenced by diminished PCYT2α mRNA and increased PCYT2β mRNA in breast cancer cells." (PMID 35563655, 2022). "In both cases, an accumulation of phosphoethanolamine (PEtn) was observed in breast cancer cells with reduced expression of PCYT2, suggesting tumor progression in response to glutamine deprivation." (PMID 33466323, 2021). "PCYT2 activity has been shown to be increased in breast cancer cells, enabling them to adapt to metabolic stress, and TRERF1 acts as a cell cycle inhibitor in breast cancer cells through the modulation of progesterone receptor." (PMID 26620706, 2015). "The activity of Pcyt2 is lower in breast cancer cells (MCF-7) in comparison to mammary epithelial cells (MCF-10A), which was confirmed at the level of promoter activity, mRNA expression, and the protein content." (PMID 23354482, 2013). "We showed that the activity of Pcyt2 was suppressed in breast cancer cells (MCF-7) cells in comparison to mammary epithelial cells MCF-10A which was evident at the level of promoter activity, mRNA expression, and protein content." (PMID 23354482, 2013). "The inhibitory effects of oxysterols and TO901317 on the Pcyt2 promoter function, mRNA and protein expression were conserved in the human breast cancer cells MCF-7." (PMID 22820672, 2008). "Since PCYT2α, PCYT2-213/PCYT2γ, and PCYT2-205 were almost exclusively expressed in control cells, the data clearly demonstrated that deviations in the PCYT2 splicing mechanism are an important aspect of breast cancer development." (PMID 35563655, 2022). "The human Pcyt2 promoter was isolated from human breast cancer cells (MCF-7)." (PMID 23354482, 2013). "In human breast cancer cells (MCF-7), the level of PCYT2 in cancer cells is elevated in response to the stressful environment." (PMID 40434993, 2025). "This included PCYT2, which was found to have a high correlation for the HER-2 positive breast cancer tumor subtype." (PMID 35563655, 2022). "PCYT2 protein alone is not currently considered a prognostic marker for breast cancer, although this may not be accurate due to the nature of antibodies used to investigate this and as will be shown here, the presence of multiple isoforms and the complexity of PCYT2 splicing." (PMID 35563655, 2022).
dyslipidemia (4 papers, 2013 to 2025). "Pcyt2+/− mice developed features of metabolic syndrome including liver steatosis because accumulating DG is shunted towards triacylglycerol synthesis." (PMID 31637422, 2019). "Multiple expression data available through GEO Database of NCBI provide the evidence for regulatory role of Pcyt2 in lipid and energy metabolism disturbance of which could lead to metabolic syndrome and related metabolic disorders." (PMID 23354482, 2013).
hereditary spastic paraplegia (4 papers, 2019 to 2025). Hereditary spastic paraplegias (HSP) comprise a genetically and clinically heterogeneous group of neurodegenerative disorders characterized by progressive spasticity and hyperreflexia of the lower limbs. "Three subsequent PCYT2 variants (Lys319Asn; Lys319Asn/Val320ins34; and Val303Ter) have been identified in patients with hereditary spastic paraplegia." (PMID 35563655, 2022). "A third variant has recently been identified that produces a truncated PCYT2 protein (p.Arg377Ter) with reduced activity, and this mutation causes hereditary spastic paraplegia." (PMID 35563655, 2022). "We describe five individuals with a complex hereditary spastic paraplegia (cHSP) and biallelic PCYT2 variants." (PMID 31637422, 2019). "Recently, mutations in PCYT2, the human counterpart of fly PECT, have been associated with hereditary spastic paraplegia." (PMID 33064773, 2020). "Interestingly, human patients harbouring loss of function mutations PCYT2 have recently been found to develop complex hereditary spastic paraplegia (HSP) and a broad ataxia-spasticity condition and implicate disturbed neuronal phospholipid metabolism as a key pathological feature." (PMID 40153413, 2025).
liver steatosis (4 papers, 2013 to 2025). "PEA supplementation was able to reverse Pcyt2+/− hepatic steatosis and inflammation." (PMID 35058529, 2022). "Thiamine mitigated visceral adipocyte hypertrophy, liver steatosis, and skeletal muscle insulin resistance without causing damage to heart or kidneys and microarray data show that Pcyt2 was up-regulated in liver of the rats who received thiamine treatment." (PMID 23354482, 2013). "We have previously shown that an 8-week treatment with the artificial Pcyt2 substrate PEA prevents and/or reverses multiple aspects of the Pcyt2 + /- NASH phenotype including liver steatosis, inflammation, and the protein levels of several glucose and fatty acids metabolic regulators." (PMID 40153413, 2025). "On the other hand, when challenged with a high-fat diet (HFD), liver-specific SIRT1 knockout mice develop hepatic steatosis, hepatic inflammation, and endoplasmic reticulum stress regardless of the up-regulation of Pcyt2." (PMID 23354482, 2013).
non-alcoholic steatohepatitis (4 papers, 2022 to 2025). "CDP-Etn supplementation has been reported to alleviate PCYT2 deficiency engendering age-dependent and insulin-resistant non-alcoholic steatohepatitis to improve patient prognosis." (PMID 40434993, 2025). "The heterozygous deletion of Pcyt2 in mice leads to hepatic DAG and TAG accumulation, providing a model of non-alcoholic steatohepatitis." (PMID 38409325, 2024).
hypertriglyceridemia (3 papers, 2013 to 2025). A laboratory test result indicating elevated triglyceride concentration in the blood. "We established that Pcyt2 deficient/HET mice lose body weight after 2 months of Bet supplementation that was attributed to reductions in organ (liver and adipose) lipids and elimination of hypertriglyceridemia." (PMID 30042948, 2018). "Mechanisms behind hypertriglyceridemia in Pcyt2+/− mice were recently investigated." (PMID 23354482, 2013).
Spastic paraplegia (3 papers, 2019 to 2023). Complete loss of the ability to move the lower limbs accompanied by spasticity of the lower limbs. "The same occurred with a PCYT2 mutation in patient IDSPG27, ranked 3 in a VCF file with 1738 variants, because PCYT2 protein interacts with other proteins associated with spastic paraplegia such as PNPLA6 or COASY." (PMID 37679823, 2023). "In summary, using genomics, lipidomics, in vitro and in vivo studies we describe a novel autosomal recessive inborn error of biosynthesis of complex lipids caused by hypomorphic PCYT2 variants resulting in a complex hereditary spastic paraplegia." (PMID 31637422, 2019). "In conclusion, our data establish PCYT2 as a disease gene for a new complex hereditary spastic paraplegia and confirm that etherlipid homeostasis is important for the development and function of the brain." (PMID 31637422, 2019).
steatosis (3 papers, 2022 to 2025). Increased lipid within the cytoplasm of cells. "All of these pathways are supported by our previous evidence showing molecular perturbations to these pathways, and the physiological consequences including reduced fatty acid oxidation, deficient insulin signalling, liver inflammation and steatosis in Pcyt2 + /- mice." (PMID 40153413, 2025). "We also showed that supplementation with the artificial Pcyt2 substrate phosphonoethylamine (PEA) reverses Pcyt2 + /- steatosis, inflammation, and improved the dysregulation of various regulators associated with NASH pathogenesis." (PMID 40153413, 2025). "H&E staining revealed adult Pcyt2+/− develop steatosis (blue circles), ballooned hepatocytes (black circles) with Mallory-Denk bodies (black arrows) and lobular inflammation (yellow arrows)." (PMID 35058529, 2022). "Hepatic inflammation is the critical factor distinguishing NASH from simple steatosis and is further demonstrated in adult Pcyt2+/− in the enrichment of proinflammatory pathways and increased mRNA/protein expression of proinflammatory modulators." (PMID 35058529, 2022). "Adult Pcyt2+/− exhibit all of the criteria for biopsy proven NASH 42: steatosis, hepatocyte ballooning degeneration with Mallory bodies, inflammatory infiltration of macrophages, and fibrosis." (PMID 35058529, 2022). "Supplementation with PEA reverses Pcyt2+/− steatosis, inflammation, and other aspects of NASH, showing that was directly caused by Pcyt2 deficiency." (PMID 35058529, 2022). "In contrast, hepatic Pcyt2+/− mice developed steatosis and had lower hepatic VLDL-C secretion." (PMID 35323651, 2022). "Thus, it is conceivable that PEA is able to improve Pcyt2+/− steatosis through stimulating metabolic flux by the Kennedy pathway, restoring membrane phospholipid homeostasis and increasing the utilization of DAG to reestablish energy balance and improve lipid and glucose metabolism." (PMID 35058529, 2022).
colon cancer (2 papers, 2013 to 2025). "Pcyt2 expression was significantly reduced in invasive human metastatic colon tumor cell lines in comparison to the primary tumor cell line." (PMID 23354482, 2013). "Pcyt2 is up-regulated in methotrexate (MTX) resistant HT29 in comparison to MTX sensitive colon cancer cell line." (PMID 23354482, 2013).
diabetes (2 papers, 2018 to 2023). "Remarkably, ∼50% of these protein-coding genes were also DE following anti-diabetes drug-treatment; including ALDH6A DHTKD1, PCYT2 and RND3 (this compares with <5% of the transcriptome responding to drug -treatment)." (PMID 29986096, 2018).
hepatocellular carcinoma (2 papers, 2025). A malignant tumor that arises from hepatocytes. "This study aimed to investigate the role of PCYT2 in human hepatocellular carcinoma cells (HepG2) by inhibiting their proliferation, invasion, and migration abilities and promoting cell apoptosis." (PMID 40434993, 2025). "Associations between aberrant methylation of intergenic regions and T2DM, liver fibrosis and hepatocellular carcinoma have recently been established, suggesting the regulation of intergenic elements during Pcyt2 + /- NASH as an interesting area in subsequent studies." (PMID 40153413, 2025). "However, the role of PCYT2 in the development of hepatocellular carcinoma (HCC) unknow." (PMID 40434993, 2025).
lipid metabolism disorders (2 papers, 2023). "Targeted quantitative lipidomics studies confirmed a pathogenic role for variants in genes associated with lipid metabolism disorders, such as PI4KA, PCYT2 and ACER3, in n = 4 cases." (PMID 37679823, 2023). "To further understand the mechanism of liver lipid metabolism disorders in T2DM, we tested the mRNA and protein levels of PCYT2 and PISD in L02 cells under HG&FFA stimulation." (PMID 36716821, 2023).
liver disease (2 papers, 2022 to 2025). "Increasing evidence suggests that PCYT2 is aberrantly expressed in various models of liver disease and may predict clinical outcomes in patients." (PMID 40434993, 2025). "Heterozygous ablation of Pcyt2 causes changes in liver metabolic regulators from young age, prior to the development of liver disease which does not occur until adulthood." (PMID 35058529, 2022).
metastatic colorectal cancer (2 papers, 2024 to 2025). "Here, we show that PCYT2 was significantly downregulated in metastatic colorectal cancer (CRC) and acted as a tumor metastasis suppressor." (PMID 39531326, 2024). "For instance, in metastatic colorectal cancer (CRC), PCYT2 is significantly downregulated and functions as a tumor metastasis inhibitor." (PMID 40434993, 2025).
non-alcoholic fatty liver disease (2 papers, 2023 to 2025). "PCYT2 is a rate-limiting enzyme in PE synthesis that is commonly used in the study of obesity-related diseases, such as non-alcoholic fatty liver disease and type 2 diabetes." (PMID 40434993, 2025).
breast adenocarcinoma (1 paper, 2022). "PCYT2 expression and activity are mostly reduced in cancers, but in breast adenocarcinoma cells metabolic stress leads to increased PCYT2 expression and activity." (PMID 35563655, 2022).
hyperhomocysteinemia (1 paper, 2026). A serious metabolic condition caused by mutations in the MTHFR gene, medications, or nutritional deficiency. "Increased PE and PCYT2 expressions were associated with more severe kidney damage induced by hyperhomocysteinemia in a 2-kidney, 1-clip mouse model." (PMID 41346700, 2026).